HTT (huntingtin)
Diseases named in the same sentence as HTT in open-access papers (continued):
Sharing a sentence is not in itself a finding about the gene and the disease.
testicular degeneration (1 paper, 2015). "In contrast, YAC128 mice develop testicular degeneration before levels of testosterone decrease and before loss of GnRH neurons in the hypothalamus can be detected, suggesting that testicular pathology results from a direct toxic effect of mutant huntingtin in the testes." (PMID 26431314, 2015).
Tics (1 paper, 2017). Repeated, individually recognizable, intermittent movements or movement fragments that are almost always briefly suppressible and are usually associated with awareness of an urge to perform the movement. "A 17-year-old boy with initial presentation of tics attended our clinic and his DNA analysis demonstrated mutation in the HTT gene (49 CAG repeats)." (PMID 28789621, 2017).
Torsion dystonia (1 paper, 2018). Sustained involuntary muscle contractions that produce twisting and repetitive movements of the body. "Instead, it was the increased level of huntingtin aggregation in the presence of the torsion dystonia-causing ΔE302/303 mutant that reached statistical significance in both neuronal and non-neuronal cells." (PMID 29641419, 2018).
neurodegenerative disease (301 papers, 2006 to 2026). A disorder of the central nervous system characterized by gradual and progressive loss of neural tissue and neurologic function. "HD is a progressive neurodegenerative disease with an autosomal dominant inheritance pattern that occurs due to a mutation in the gene that encodes the Huntingtin (Htt) protein." (PMID 40563824, 2025). "This hereditary neurodegenerative disease is caused by cytosine–adenine–guanine (CAG) trinucleotide repeats in the first exon of the HTT gene that encodes Huntingtin (HTT)." (PMID 38931834, 2024). "Huntington’s disease (HD) is an inherited neurodegenerative disease caused by an abnormal expansion in the polyglutamine (polyQ) tract of the N-terminal Huntingtin (Htt-ex1) protein." (PMID 37101557, 2023). "HD is a progressive neurodegenerative disease caused by the expression of mHTT in which the CAG trinucleotide repeats are expanded at the exon 1 of the HTT gene." (PMID 37117485, 2023). "Neurodegenerative disease-causing proteins such as alpha-synuclein, tau, and huntingtin are known to traverse across cells via exosomes, extracellular vesicles and tunneling nanotubes (TNTs)." (PMID 37396786, 2023). "HD is a neurodegenerative disease that results from a mutation in the HTT gene, which encodes huntingtin." (PMID 37891890, 2023). "Polyglutamine expansion at the N-terminus of the huntingtin protein exon 1 (Htt-ex1) is closely associated with a number of neurodegenerative diseases, which result from the aggregation of the increased polyQ repeat." (PMID 37101557, 2023). "Other polyQ-containing proteins such as ATXN7 and huntingtin are associated with the development of neurodegenerative diseases when their N-terminal polyQ domains are expanded." (PMID 38128014, 2023). "Huntington's disease (HD) is a fatal neurodegenerative disease caused by an expanded polyglutamine (polyQ) domain in the huntingtin protein (htt; Macdonald, 1993)." (PMID 37052951, 2023). "HD is a neurodegenerative disease caused by heterogeneous aggregation of mutated huntingtin proteins with normal huntingtin proteins." (PMID 37489365, 2023). "The cause of this neurodegenerative disease is a mutation in the gene called huntingtin (HTT), located on chromosome 4 of the human being." (PMID 35526033, 2022). "The abnormal structure of the pathogenic proteins such as LRRK2, Tau, HTT and the aggregation of specific proteins such as polyQ and α-Syn can be the hallmarks of neurodegenerative diseases and have great potential in precision medicine." (PMID 37288246, 2022). "HD is an autosomal dominant, neurodegenerative disease manifesting as progressive chorea, rigidity, dementia, and psychiatric disturbance caused by accumulation of the mutant HTT gene in neural and somatic cells." (PMID 36555531, 2022). "HD is a hereditary, neurodegenerative disease caused by cytosine–adenine–guanine (CAG) repeat expansion in the huntingtin (HTT) gene, which codes for glutamine." (PMID 35327542, 2022). "HD is a progressive neurodegenerative disease caused by a trinucleotide (CAG) expansion in exon 1 of the Huntingtin (HTT) gene, resulting in the expression of an expanded, mutant huntingtin protein (mHTT)." (PMID 33920577, 2021). "To expand the disease spectrum beyond the NMD field, we studied the HTT gene, mutations in which cause HD, an autosomal dominant, lethal, neurodegenerative disease." (PMID 34744760, 2021). "HD is a hereditary neurodegenerative disease caused by expansion of a polyglutamine (polyQ) stretch in the huntingtin (HTT) protein." (PMID 32492924, 2020).
neurodegenerative disease (continued). "A third neurodegenerative disease to be mentioned here, HD, is an inherited and incurable neurodegenerative disease caused by trinucleotide repeat (CG) in the huntingtin (HTT)-encoding gene, which causes significant motor, cognitive, and psychiatric deficits." (PMID 32252470, 2020). "HD is an inherited neurodegenerative disease caused by a CAG triplet (encoding glutamine) repeat expansion in the huntingtin (HTT) gene that causes HTT protein to misfold and aggregate." (PMID 30941017, 2019). "Huntington’s (HD) is another neurodegenerative disease caused by a polyglutamine repeat sequence in the huntingtin protein, which inhibits HATs leading to a decrease of H3 and H4 histone acetylation." (PMID 30279699, 2018). "Our group first demonstrated in HD, another progressive neurodegenerative disease, that elevated expression of Grb2 in HD animal and cell models reduces aggregation of mutant Huntingtin (Htt) protein, the hallmark of HD." (PMID 28360125, 2017). "Many altered neuronal proteins that hallmark neurodegenerative diseases (such as the amyloid, α-synuclein, and huntingtin) are physiologic substrates of cathepsin D and would abnormally accumulate if not efficiently be degraded by this enzyme." (PMID 29183303, 2017). "Huntington’s disease (HD) is a fully penetrant neurodegenerative disease caused by a dominantly inherited CAG trinucleotide repeat expansion in the Huntingtin gene (HTT)." (PMID 28422761, 2017). "For instance, HD is a neurodegenerative disease caused by an expansion of CAG triplicate repeats in the Huntingtin gene (Htt)." (PMID 25681390, 2015). "Recently proteins directly implicated in the most prevalent neurodegenerative diseases, such as amyloid-β precursor protein, tau, α-synuclein, prion protein and huntingtin, have been connected to neuronal iron homeostatic control." (PMID 24795635, 2014). "Autophagy has been shown to play a role in several long-lived proteins associated with neurodegenerative disease, including huntingtin, synuclein, and beta-amyloid (Aβ)." (PMID 24454378, 2013). "Huntington disease (HD) is a devastating inherited neurodegenerative disease caused by a CAG trinucleotide repeat expansion in exon 1 of huntingtin (Htt) gene." (PMID 23469253, 2013). "Huntington’s disease (HD) is a neurodegenerative disease caused by abnormal polyglutamine expansion in the huntingtin protein (Htt)." (PMID 23967334, 2013). "Mutations or overexpression in neurodegenerative disease genes, including presenilin, huntingtin (Htt), α-synulcien, parkin, and PINK1, have been reported to inhibit macroautophagy." (PMID 23300858, 2012). "Chemokines havebeen implicated in the pathogenesis of other neurodegenerative diseases and interesting recent results link the expression of mutant huntingtin in neuronsto increased expression of chemokines." (PMID 21826115, 2011). "Neurodegenerative disease-causing mutations like mutated huntingtin have been linked to mitochondrial dysfunction, and an impairment of mitochondrial activity has been observed in cells and tissues isolated from patients with neurodegenerative diseases." (PMID 20701773, 2010). "In other proteins, glutamine-rich domains have been implicated in protein aggregation, such as in certain neurodegenerative diseases that involve the formation of long-lived protein aggregates (e.g., the PolyQ domain of mutant Huntingtin)." (PMID 16934003, 2006). "This phenomenon extends beyond β-amyloid and tau, with interactions of sleep impairment with the homeostasis of TDP-43, α-synuclein, FUS, and huntingtin proteins, implicating sleep loss as an important consideration in an array of neurodegenerative diseases and in cases of mixed neuropathology." (PMID 37085942, 2023). "Furthermore, mutations of torsin A have been associated with increased level of huntingtin aggregation, and it has been observed in Lewy bodies and Lewy neurites in substantia nigra and cortex, thus likely being implicated in neurodegenerative diseases." (PMID 34575134, 2021).
neurodegenerative disease (continued). "Among the heterogeneous group of neurodegenerative diseases, it takes a special role based on its strictly genetic cause, i.e., an autosomal dominant mutation of the huntingtin (HTT) gene on chromosome 4 (The Huntington’s Disease collaborative research group, 1993)." (PMID 32116525, 2020). "The N terminal fragments of mutant HTT (mHTT) is prone to misfolding and aggregation, a feature shared with pathogenic proteins implicated in other neurodegenerative diseases." (PMID 28611571, 2017). "Interestingly, it has been found that trehalose can also work as a potent activator of autophagy, and facilitates clearance of mutant huntingtin and other aggregation-prone proteins associated with the neurodegenerative diseases." (PMID 29019918, 2017). "We propose that this method of stable isotope labeling, and its applicability to studying the clearance of proteins in genetically modified mouse models, will be useful in studying the kinetics of proteins implicated in other neurodegenerative diseases, such as synuclein, tau, and huntingtin." (PMID 22512932, 2012). "Protein polymerization seems to have a central role in the progression of the prion pathology, an aspect shared with several other neurodegenerative diseases associated with different aggregating proteins, such as Alzheimer's (A ), Parkinson's (-synuclein) and Huntington's (huntingtin) diseases." (PMID 19578427, 2009). "By elucidating the intricate relationship between HTT and neuronal autophagy, this review aims to shed light on specific mechanisms of action in autophagy that can be disrupted in neurodegenerative diseases including HD." (PMID 40475846, 2025). "Several neurodegenerative disease proteins have been shown to be O-GlcNAcylated such as tau, α-synuclein, huntingtin, and more importantly, TDP-43." (PMID 40619440, 2025). "There is a growing body of evidence suggesting a role for the HTT gene in both healthy individuals and patients affected by neurodegenerative diseases." (PMID 40844528, 2025). "USP14 inhibition activates the proteasome, removes tau oligomers, and promotes huntingtin aggregation, suggesting that it contributes to aggregate deposition in neurodegenerative diseases." (PMID 38780644, 2024). "The effects of USP14 inhibition on aggregates, such as tau and huntingtin, in neurodegenerative diseases are controversial." (PMID 38780644, 2024). "Several neuronal proteins considered hallmarks of neurodegenerative diseases, such as the amyloid precursor, α-synuclein, and huntingtin, are physiologic substrates of CTSD." (PMID 37958719, 2023). "Studies have shown that deletion in HTT gene prevents embryos from developing normally, leading to premature embryonic death and Htt gene knock out in adulthood induces neurodegenerative diseases." (PMID 36998046, 2023). "HD is a progressive neurodegenerative disease characterized by expanded CAG repeat in the gene encoding huntingtin, resulting in abnormally long polyglutamine (polyQ) repeat in the huntingtin protein." (PMID 35955427, 2022). "Future missions should address the impact of spaceflight on glial clearance pathways, particularly in the presence of proteostressors such as neurodegenerative disease proteins tau, Aβ, huntingtin, or alpha-synuclein." (PMID 33659873, 2021). "14-3-3 proteins interact with multiple aggregation-prone proteins in neurodegenerative diseases, including tau, huntingtin, and αsyn." (PMID 33413679, 2021). "Calcium dyshomeostasis is a common event during pathophysiological processes of neurodegenerative diseases, and huntingtin, with its expanded polyglutamine stretch, is an ideal candidate substrate for transglutaminases." (PMID 34445621, 2021). "In other mouse models of neurodegenerative diseases, autophagy induction was also found to promote the clearance of different aggregated proteins including huntingtin, α-synuclein and amyloid beta." (PMID 33413517, 2021).
neurodegenerative disease (continued). "HD is a neurodegenerative disease caused by the repetition of CAG in the huntingtin gene, which leads to huntingtin protein (HTT) aggregation, inducing neuronal death, mainly in the corpus striatum but also in systemic cells." (PMID 34356637, 2021). "Critical proteins that unfold and aggregate in neurodegenerative diseases, such as α-synuclein, tau, huntingtin (Htt), and polyglutamine androgen receptor (polyQ AR), are client proteins of heat shock protein 90 (HSP90)." (PMID 33542205, 2021). "It is a fatal neurodegenerative disease, caused by an abnormal triplet repeat expansion of CAG (cytosine-adenine-guanine) within the huntingtin (HTT) gene on chromosome 4p16.3, causing a mutated huntingtin protein (mHTT)." (PMID 31940909, 2020). "HD is a neurodegenerative disease arising from an expanded CAG repeat in the exon 1 of the huntingtin gene, which translates into a polyglutamine (polyQ) tract in the huntingtin (Htt) protein 1,2." (PMID 32327686, 2020). "In neurodegenerative disease, abnormal accumulation of neuronal proteins (e.g., the amyloid precursor, α-synuclein, and huntingtin) are due to diminished or abolished activity of Cathepsin D." (PMID 31091796, 2019). "For example, neurodegenerative disease-related protein aggregates, such as polyglutamine, huntingtin, ataxin-1, and superoxide dismutase-1, block clathrin-mediated endocytosis and intracellular trafficking in neurodegenerative disease." (PMID 30866990, 2019). "Several neurodegenerative disease proteins including Aβ, tau, α-syn, mutant huntingtin, mutant SOD1, and TDP-43 misfold and self-propagate through templated recruitment." (PMID 30310141, 2018). "A common theme for the development of neurodegenerative diseases is the propensity of a number of proteins, such as α-synuclein, Huntingtin (HTT), and Tau, to misfold and form insoluble aggregates." (PMID 28700687, 2017). "HTT, the fourth most significant gene, is related to heart diseases and its full name is Huntingtin, which is naturally related to the corresponding neurodegenerative disease." (PMID 29322921, 2017). "Rimming of pathological aggregate structures was reported in other neurodegenerative diseases, e.g., the rimming of huntingtin aggregates by p62 or HDAC6." (PMID 27481264, 2016). "Caspase-6 has also been proposed to be involved in the cleavage of neurodegenerative disease-related proteins, such as huntingtin in Huntington’s disease (HD)." (PMID 26505998, 2015). "Recent literature has revealed the protective role of autophagy in neurodegenerative diseases through degradation of mutant toxic proteins, including huntingtin or α-synuclein." (PMID 25699594, 2015). "Mitochondrial dysfunction is thought to be a key event in some neurodegenerative diseases, and mutant huntingtin has been shown to trigger mitochondrial fragmentation by stimulating DRP1, the mitochondrial fission GTPase dynamin-related protein-1." (PMID 24424024, 2014). "For instance, it includes the Huntingtin gene which is especially interesting in context of neurodegenerative diseases." (PMID 24098440, 2013). "Huntington disease (HD) is an inherited neurodegenerative disease resulting from an abnormal expansion of polyglutamine in huntingtin (Htt)." (PMID 23469253, 2013). "We also found that PEA metabolism is affected by heterologous expression of two mammalian proteins involved in neurodegenerative diseases, namely huntingtin and α-synuclein." (PMID 19529773, 2009). "We saw that these genes of interest could be linked to known familial neurodegenerative disease genes (APP and HTT), and AD risk genes (APOE and PLCG2) from prior experimental studies using the Ingenuity database." (PMID 39231932, 2024). "The importance of metal biology in neurodegenerative diseases such as Huntingtin Disease is well documented with evidence of direct interactions between metals such as copper, zinc, iron and manganese and mutant Huntingtin pathobiology." (PMID 35725749, 2022).